RNU6-919P (RNA, U6 small nuclear 919, pseudogene)
Gene: Small nuclear RNA gene on chromosome 20 (49,794,811 to 49,794,914, forward strand). Ensembl gene ENSG00000252540.
Homologues: Orthologues: chimpanzee U6 (98% identical), macaque U6 (92% identical), dog U6 (79% identical), mouse Gm25622 (76% identical), mouse Gm25600 (72% identical). Paralogues in human: RNU6-97P (88% identical), RNU6-1094P (86% identical), RNU6-1131P (86% identical), RNU6-509P (86% identical), RNU6-1340P (85% identical), RNU6-379P (85% identical), RNU6-43P (85% identical), RNU6-820P (85% identical), RNU6-1025P (84% identical), RNU6-108P (84% identical), RNU6-1127P (84% identical), RNU6-11P (84% identical), and 1287 more.